NRP1 (neuropilin 1)
Diseases named in the same sentence as NRP1 in open-access papers (continued):
Sharing a sentence is not in itself a finding about the gene and the disease.
tumor (continued). "Within the included studies, NRP1 levels determination was performed mainly in the tumor tissue; nevertheless, three articles analyzed serum NRP1 levels." (PMID 35884516, 2022). "The role of Nrp1 on tumor cells with respect to stemness, radiation resistance and targeted treatment resistance will also be considered." (PMID 36203599, 2022). "The overexpression of NRP-1 and its interaction with vascular endothelial growth factor-165 (VEGF165) are associated with tumor growth and metastasis." (PMID 35056995, 2022). "Tumor growth was suppressed in mice in the shNRP1 group compared to control, and tumor volumes from post-inoculation week 7 onwards were significantly lower in the NRP1-suppressed group." (PMID 35078508, 2022). "Cluster M0 highly expressed immunosuppressive and angiogenic phenotype-related markers (SLC40A1, NRP1, and CD36) and promote tumor progression associated with markers (CD163 and CD163L1)." (PMID 35265520, 2022). "As a response to Sema3A, NRP-1 plays a key role in the entry of TAMs into hypoxic niches, but the loss of NRP-1 promotes anti-tumor immunity and hinders angiogenesis." (PMID 36419156, 2022). "Next, the mRNA and protein expression levels of GATA3 and NRP1 in tumor tissues also confirmed our conjecture." (PMID 35993027, 2022). "In TDLNs of patients after CRT, Tregs and Nrp1+Tregs dropped in relation to reduction of tumor mass." (PMID 35566403, 2022). "Prior work demonstrated that Neuropilin-1 (Nrp1), a co-receptor expressed on the surface of microglia and macrophages, sustains a robust neoangiogenic program as well as an immunosuppressive tumor microenvironment." (PMID 36203599, 2022). "NRP1 recruits and subsequently arrests pro-tumorigenic TAMs in response to Sema3A-producing hypoxic tumor regions through plexinA1/plexinA4 signaling and VEGFR1 activation." (PMID 35651620, 2022). "Tumor tissue NRP-1 and its soluble isoforms in plasma are upregulated in advanced nodal and metastatic BC, and tumor tissue NRP-1 expression is increased in TNBC compared to other subtypes." (PMID 35158858, 2022). "Nrp-1 and Nrp-2 have been shown to be expressed on DCs, macrophages, and T-cell subpopulations and mainly exert pro-tumor effects." (PMID 35155237, 2022). "Sema3A and Sema3B, constitutively distributed on immune cells, binding to Nrp-1, contribute to immune escape from anti-tumor effects of CD8+ CTL." (PMID 35155237, 2022). "A newer version of AGuIX, which includes porphyrin as an extra photosensitizer and is modified with peptides targeted to neuropilin-1 (NRP-1), a transmembrane receptor abundantly overexpressed in the tumor vascular system, is undergoing preclinical testing." (PMID 35631503, 2022). "Exhausted T cells not only highly express PD-1 and CTLA-4, but also highly express semaphorins and their receptors, especially Nrp-1; thus, tumor cells are compromised to immune checkpoint inhibitors and turn to self-tolerance." (PMID 35155237, 2022). "Researchers have shown that targeting 4D phosphodiesterase, interacting directly with NRP1, inhibits tumor growth in vivo, even in mice resistant to vismodegib, an anti-SMO treatment." (PMID 34277411, 2021). "The tumor penetrating peptides contain the CendR recognition domain responsible for the neuropilin-1 dependent internalization." (PMID 33918106, 2021). "Neuropilin-1 (Nrp1) is a transmembrane receptor that is critical for the function and stability of tumor infiltrating Tregs." (PMID 33801234, 2021). "Inhibition of PlGF/NRP1 decreases tumor growth and metastasis in mice, and increases their survival rate." (PMID 34277411, 2021). "It has also been reported that the neutralization of VEGF and NRP-1 suppresses vascular remodeling and tumor growth." (PMID 33836774, 2021). "Tumor cell proliferation and survival, angiogenesis, metastasis formation, and tumor immune escape include a series of mechanisms involving NRP-1 at different levels." (PMID 34359721, 2021).
tumor (continued). "Higher levels of expression of mesenchymal-associated genes SNAI1, SERPINE1, MSN, NRP1 and LAMC2 were observed in CTCs compared to primary tumour in three of the four models (the exception being LuCaP96)." (PMID 34206049, 2021). "Further studies demonstrated that the nuclear localization of FUBP1 contributed to tumor immune evasion by regulating the expression of NRP1." (PMID 33987449, 2021). "Intriguingly, while NRPs can bind many tumor-suppressor semaphorins, they are in fact considered tumor-promoting molecules per se; thus, NRP1 targeting is gaining increasing interest for cancer therapy, independent of semaphorin functions 107,108." (PMID 33537086, 2021). "Tumor angiogenesis is recognized as a crucial phenomenon in the progression of malignant tumors and is correlated with overexpression of the neuropilin-1 (NRP-1) receptor." (PMID 34885871, 2021). "This motif has to be C-terminally exposed to allow tumor-specific binding and penetration via the Neuropilin-1 (NRP-1) receptor." (PMID 34683924, 2021). "The VEGFs coreceptors, Neuropilins 1, 2 (NRP1, 2) are expressed on several tumor cells including ccRCC." (PMID 33461580, 2021). "In the harsh tumor microenvironments, the immunoregulatory receptor Neuropilin-1 (NRP1) is very important to maintain the function, integrity, and survival of intertumoral regulatory T cells (Treg cells)." (PMID 33987449, 2021). "Elevated NRP1 expression was detected in malignant cells and in tumor microenvironment (TME) on macrophages, Treg cells, CD8+ T cells, and dendritic cells (DCs)." (PMID 34961486, 2021). "Juxtacrine interaction between NRP1-expressing tumor cells and VEGFR2-endothelial cells can occur in vitro in the presence of VEGF16558." (PMID 33859199, 2021). "NRP1 is found to be upregulated in several types of cancer and favors tumor cell growth, survival and metastasis." (PMID 34168096, 2021). "Inducible T cell costimulator (ICOS), glucocorticoid-induced tumor necrosis factor receptor (GITR), or neuropilin 1 (Nrp-1) induce the proliferation and effector functions of Treg cells and their tumor infiltration." (PMID 33923750, 2021). "According to the targeting theory of the iRGD peptide, the peptide can realize extravasation and tumour‐specific penetration by binding αvβ3 or αvβ5 and NRP‐1 on the tumour vascular endothelium and various tumour cells." (PMID 34213835, 2021). "Neuropilin 1 (NRP1) as a coreceptor of growth factors is involved in tumor progression that affects tumor cell viability through EGFR and ErbB2 signaling pathways." (PMID 33827418, 2021). "C-terminally exposed CendR motif binds to neuropilin-1 (NRP-1) to trigger endocytic transport and tumor penetration pathway named CendR pathway." (PMID 33444445, 2021). "Overexpression of NRP-1 in vitro and in vivo correlates with decreased tumor vascularization and apoptosis, suggesting a direct correlation between level of NRP-1 expression and aggressiveness of the tumor." (PMID 34683924, 2021). "The R/KXXR/K motif (arginine/lysine, two hydrophobic amino acids, arginine/lysine) interacts with neuropilin 1 or 2 receptors of cancer cells, and then enter by endocytosis, thus increasing the efficiency of these peptides to cross tumor barriers." (PMID 33919639, 2021). "Our data show that PLEXIND1 knockdown downregulates tumor growth and that there is upregulation of NRP1 in KRASmut cells." (PMID 34439202, 2021). "Depletion of NRP1 decreased in vitro cell proliferation and dramatically prevented D2.A1 tumor formation within the pulmonary microenvironment, following tail vein inoculation of equal numbers of viable cells." (PMID 33128042, 2021). "Recent studies have supported NRP1 as a potential tumor anti-angiogenesis therapeutic target, and NRP1-neutralizing antibodies or small-molecule antagonists have been shown to suppress tumor growth in an additive manner to VEGF neutralization." (PMID 34150622, 2021).
tumor (continued). "NRP1 appears to influence the tumor cell proliferation and migration by interacting with various proteins and signaling pathways." (PMID 34277411, 2021). "This peptide binds to a tumor-specific receptor, after which it is proteolytically cleaved and then binds to a second receptor, neuropilin-1, resulting in activation of the CendR pathway." (PMID 34204007, 2021). "We observed the accumulation of LinTT1‐DiR‐PS in the extravascular tumor parenchyma and their co‐localization with the known receptors of LinTT1 peptide, p32, and NRP‐1." (PMID 33908690, 2021). "First, we analysed the expression profile of NRP1 in 600 pairs of CRC tumor tissues and adjacent normal tissues from The Cancer Genome Atlas (TCGA)." (PMID 33846300, 2021). "Here, we demonstrated a new regulatory axis in the hypoxic tumor microenvironment involving elevated NRP1 expression induced by HIF-1α." (PMID 33850110, 2021). "Conversely, in BxPC-3 cells, PLEXIND1 reduction enhances tumor growth, and there is upregulation of NRP1; we have earlier published that NRP1 facilitates tumor growth in BxPC-3 cells." (PMID 34439202, 2021). "Considerable research has shown that the residual peptide, CRGDK/R, the product of iRGD hydrolyzation, is the specific ligand of NRP-1, which is highly expressed in tumor tissues." (PMID 34616773, 2021). "Collectively, all these results demonstrated that NRP1 expression was induced by HIF-1α in the hypoxic tumor microenvironment." (PMID 33850110, 2021). "Further, many studies have observed the abnormally high expression of NRP1 in multiple tumor types, including neuroblastomas and bile duct, gastric, pancreas, lung, prostate, breast, and colon cancers." (PMID 34249735, 2021). "While the reasons for this result remain to be definitively determined, previous studies have demonstrated that anti-NRP1 antibodies first saturate host pulmonary tissues prior to binding to tumor cells." (PMID 33128042, 2021). "Studies have shown that NRP1 regulates vascular endothelial factor (VEGF) to promote tumor angiogenesis." (PMID 34843522, 2021). "It was indicated that the highly expression of NRP1 was related to tumor maximum diameter greater than 5cm, deeper invasion, severe lymph node metastasis, distant metastasis, later TNM stage, and shorter OS." (PMID 33995640, 2021). "Data show that neutralizing NRP1 with a specific antibody improves the migration of LT CD8+ infiltrating the tumor and their cytotoxicity." (PMID 34277411, 2021). "NRP1 has been reported to interact with numerous ligands and receptors to promote tumor progression and EMT in a number of different cancers." (PMID 33846300, 2021). "There are several lines of evidence showing that NRP-1 mediates angiogenesis and that increased NRP-1 expression correlates with a decrease in tumor progression, angiogenesis, and immune evasion." (PMID 34683924, 2021). "Co-administration of a cell-penetrating peptide with a tumor-targeting drug allowed the drug to penetrate into tumor’s extravascular space in a tumor-specific and neuropilin-1-dependent manner." (PMID 34204007, 2021). "The dual targeting of both integrin αvβ3 and NRP-1 resulted in a better selectivity and uptake and retention into the tumor." (PMID 34885871, 2021). "The expression of miR-25, SIRT6, Lin28b, and NRP-1 in tumor tissues was measured by western blot assay and qRT-PCR." (PMID 33510943, 2021). "Significantly, we previously published that NRP1 acts as a tumor suppressor in PANC-1 cells, and TGFβ induction downregulates its expression." (PMID 34439202, 2021). "Inhibition of NRP1 expression in ECSs reduces spheroids formation, their invasion and migration, and thus decreases tumor development." (PMID 34277411, 2021). "MUC1 induces angiogenesis in tumor microenvironments by increasing the expression of neuropilin-1 (NRP1, a co-receptor of VEGF) and its ligand VEGF." (PMID 34207342, 2021).
tumor (continued). "Subsequently, the iRGD peptide was bound to NRP-1, a receptor protein of tumor cells, to mediate the anti-tumor effect." (PMID 34616773, 2021). "Of note, a high NRP-1 expression significantly correlated with a shorter overall survival rate in both the tumor subsites." (PMID 34359721, 2021). "NRP-1 plays a multisystem role in angiogenesis, tumor progression, viral entry, axonal guidance within the central and peripheral nervous systems, and immune function." (PMID 33395426, 2021). "In hypoxic areas of tumor hypoxia-induced SEMA3A attracts TAMs by activating VEGFR1 through the composition of neuropilin-1 (Nrp1) and plexinA1/plexinA4." (PMID 34209679, 2021). "NRP1 is not only closely related to the occurrence and development of tumors and tumor immunity, but also related to vascular development." (PMID 34843522, 2021). "NRP1 is considered to regulate tumor migration, invasion, and angiogenesis as a receptor for some cancer factors or interacting with certain signaling pathways (ERK1/2, P38 MAPK, Stat5, and Akt, etc) 14-16." (PMID 33995640, 2021). "NRP1 interacts with integrin beta-1 in pancreatic ductal adenocarcinoma to promote tumor growth and invasion." (PMID 34843522, 2021). "Western blot analysis of tumor homogenates also showed downregulation of NRP-1, cyclin E, CDK2 and N-cadherin, and upregulation of p27 and E-cadherin in miR-124-3p mimics-treated tumors." (PMID 33912463, 2021). "As a ligand, the iRGD peptide can interact with tumor cells with high expression of the neuropilin-1 (NRP-1) receptor, mediate the cell membrane penetration effect, and effectively kill the tumor." (PMID 34616773, 2021). "A peptide, specifically targeting Plexin-A1, has shown promising results in reducing proliferation and angiogenesis as well as blocking tumor cell spread following disruption of NRP1 and Plexin-A1 heterodimerization." (PMID 34277411, 2021). "iRGD peptide (CRGDKGPDC) helps to promote extravasation and specific penetration by interacting with integrin αvβ3 (αvβ3) or αvβ5 and neuropilin‐1 (NRP‐1) on the tumour vascular endothelium and tumour cells, which shows great potential for tumour targeting." (PMID 34213835, 2021). "iRGD is then proteolytically cleaved in the tumor and, despite losing much of its integrin-binding activity, the truncated peptide gains affinity for NRP1 because of the C-terminal exposure of a CendR motif." (PMID 33947161, 2021). "More recently, circulating and tumor tissue expression of NRP-1 were found to increase in advanced nodal and metastatic BC." (PMID 33884469, 2021). "In juxtacrine signaling, at the same time, VEGF binds to VEGFR2 on ECs and to NRP-1 on tumor cells to induce angiogenesis and tumor growth, respectively." (PMID 33836774, 2021). "NRP1 functions as a promoter of proliferation, survival, and migration/invasion of tumor cells and endothelial cells in various tumor type." (PMID 34946938, 2021). "The expression of NRP1 was closely related to maximum tumor diameter, invasion depth, lymphnode metastasis, distant metastasis, and advanced TNM stage, and was an independent prognostic factor for overall survival (OS) in GC patients." (PMID 33995640, 2021). "Invalidation of NRP1 or NRP2 in RENCA cells delayed tumor incidence (percentage of mice with a tumor) as compared to the control group, in nude mice." (PMID 33461580, 2021). "This complex is only functional in presence of NRP1 and allows the activation of Rac 1, which is an actor of tumor cells survival." (PMID 34277411, 2021). "In combination, when NRP1 or GIPC-1 expression is suppressed, both RhoA and p38 MAPK activity is decreased, leading to the loss of the ECS phenotype and reduce tumor growth." (PMID 34277411, 2021). "NRP-1 is also expressed in tumor angiogenic vessels and some tumor cells and seems to be a target of choice for tumor imaging." (PMID 34885871, 2021).
tumor (continued). "In the present study, we investigated the contribution of NRP-1 on tumor motility and angiogenesis in a repopulated tumor that survived 10 Gy of X-ray irradiation using H1299-IR cells." (PMID 34698100, 2021). "Taken together, these findings suggest that the expression levels of tumor-suppressive miR-185-3p are associated with the intracellular levels of AGO2 and that NRP1 is a direct target of miR-185-3p in CRC cells." (PMID 33846300, 2021). "We previously reported that NRP1 acted as a tumor suppressor in PANC-1 cells, in accordance with our current findings." (PMID 34439202, 2021). "NRP-1 also regulates tumor biology, and high expression levels of tissue NRP-1 have been associated with a poor prognosis." (PMID 33884469, 2021). "Analysis of the TCGA database showed that the NRP2 pathway, more than the NRP1 pathway correlates with tumor aggressiveness only in metastatic patients." (PMID 33461580, 2021). "This supports our earlier work, where we demonstrated that NRP1 downregulation in BxPC-3 cells leads to decreased cell viability and tumor growth." (PMID 34439202, 2021). "They showed that overexpression of MUC1 in over 80% of PDA patients and its aberrant expression increases the levels of NRP-1 and VEGF, which subsequently causes a pro-angiogenic tumor microenvironment." (PMID 33836774, 2021). "PAS peptide enlarges hydrodynamic volume and RGDK improves inhibition of tumor cell growth through specific affinity with integrin αvβ3/5 and neuropilin-1, which are overexpressed by a wide range of tumor cells." (PMID 34821660, 2021). "We found that the mRNA levels of NRP1 were higher in normal tissues than in tumor tissues, but there was an increasing tendency of NRP1 from stage I to stage IV, and patients with high expression of NRP1 had a poor prognosis." (PMID 33846300, 2021). "NRP1 is overexpressed in a variety of tumor tissues and is involved in the development of axon guidance and remyelination, immune response, angiogenesis, cell survival, migration, and invasion." (PMID 33850110, 2021). "It has been previously demonstrated that NRP1 regulation by various miRNAs plays an important role in mediating tumor growth and angiogenesis." (PMID 31898520, 2020). "Findings from our previous work, supported by the present study, suggest that the NRP1 expression pattern, not only the overall expression levels, is of critical importance for tumor progression and patient prognosis." (PMID 31880322, 2020). "In prostate cancer, elevated NRP1 levels stimulated by VEGF inhibit tumor cell apoptosis and angiogenesis and are synonymous of shorter survival." (PMID 32766254, 2020). "Coadministration of PL3-AgNPs with blocking rabbit polyclonal antibodies against either TNC-C or NRP-1 resulted in a decrease in tumor homing, and a cocktail of both antibodies almost completely inhibited the tumor accumulation." (PMID 32242067, 2020). "In TME, Nrp1 is very important for maintaining the function, integrity and survival of Tregs and thus functions to suppress anti-tumor immune response." (PMID 33344447, 2020). "Similar results were shown for NRP1 expression in perivascular tumor cells (HR = 0.4, 95% CI = 0.2–0.7, p‐value = 0.003)." (PMID 31880322, 2020). "We have previously reported that immunoglobulin Fc-fused TPP11 (Fc-TPP11) enhances vascular permeability and increases paracellular permeability in tumor tissues by inducing cellular internalization of NRP1." (PMID 32560565, 2020). "Of the 64 RCC patients in the discovery cohort, samples from 63 patients yielded informative staining of which 47 (75%) were positive for tumor cell‐NRP1, 45 (72%) for perivascular NRP1 and 22 (35%) for endothelial cell expressed NRP1." (PMID 31880322, 2020). "NRP1 knockdown inhibited GC cell growth, migration and invasion in vitro, while suppressed GC xenograft tumor development in vivo." (PMID 32508529, 2020).